RN7SL282P (RNA, 7SL, cytoplasmic 282, pseudogene)
Gene: Miscellaneous RNA gene on chromosome 18 (6,601,540 to 6,601,836, forward strand). Ensembl gene ENSG00000243591.
Homologues: Orthologues: chimpanzee Metazoa_SRP (99% identical), macaque Metazoa_SRP (88% identical). Paralogues in human: RN7SL2 (79% identical), RN7SL1 (79% identical), RN7SL3 (77% identical), RN7SL478P (77% identical), RN7SL556P (77% identical), RN7SL7P (77% identical), RN7SL743P (76% identical), Metazoa_SRP (76% identical), RN7SL126P (76% identical), RN7SL47P (76% identical), RN7SL50P (76% identical), RN7SL627P (76% identical), and 702 more.